DENND10 (DENN domain containing 10)
Description:
Guanine nucleotide exchange factor (GEF) regulating homeostasis of late endocytic pathway, including endosomal positioning, maturation and secretion, possibly through activating Rab proteins such as RAB27A and RAB27B. Promotes the exchange of GDP to GTP, converting inactive GDP-bound RAB27A and RAB27B into their active GTP-bound form.
Synonyms: FAM45A
Tractability: PROTAC: ubiquitination databases record sites on it.
Gene: Protein-coding gene on chromosome 10 (119,104,086 to 119,137,984, forward strand). Ensembl gene ENSG00000119979.
Subcellular location: Late endosome
Subcellular location (Human Protein Atlas): Vesicles
Gene Ontology:
Molecular function: guanyl-nucleotide exchange factor activity; protein binding; small GTPase binding
Biological process: endosome transport via multivesicular body sorting pathway; protein transport; regulation of early endosome to late endosome transport; endocytic recycling
Cellular component: late endosome; endoplasmic reticulum membrane; endosome membrane
Genetic constraint (gnomAD): Loss-of-function variants: 13 observed, 19.1 expected, observed/expected ratio (o/e) 0.68, 90% interval 0.44 to 1.08. The upper end of that interval is the gene's LOEUF score, 1.08, which puts it in group 4 of 6, group 1 being the genes least tolerant of losing a copy. Missense variants: 182 observed, 248.52 expected, observed/expected ratio (o/e) 0.73, 90% interval 0.65 to 0.83. Synonymous variants: 81 observed, 95.21 expected, observed/expected ratio (o/e) 0.85, 90% interval 0.71 to 1.02.
Homologues: Orthologues: chimpanzee DENND10 (99% identical), macaque DENND10 (98% identical), guinea pig DENND10 (92% identical), dog DENND10 (91% identical), pig DENND10 (91% identical), rabbit DENND10 (91% identical), mouse Dennd10 (90% identical), rat Dennd10 (90% identical).
Diseases named in the same sentence as DENND10 in open-access papers:
DENND10 is named in the same sentence as 7 diseases in open-access papers, as found by Europe PMC text mining. Sharing a sentence is not in itself a finding about the gene and the disease. The quoted sentences say what the papers report.
breast carcinoma (1 paper, 2024). "DENND10 expression levels are associated with adverse prognosis of breast cancer patients." (PMID 38987765, 2024). "Intriguingly, high expression of DENND10 was significantly correlated with poor relapse-free survival (p = 0.00041) in breast cancer patients." (PMID 38987765, 2024). "Consistent with this notion, high DENND10 expression was correlated with shorter distant-metastasis free survival in a public breast cancer dataset (GSE46563)." (PMID 38987765, 2024). "Taken together, these results indicated that DENND10 is important for the migration potential of breast cancer cells." (PMID 38987765, 2024). "Our findings suggest that DENND10 modulates the migration and metastasis potential of breast cancer cells." (PMID 38987765, 2024). "In this study, we found that the endosomal protein DENND10 is involved in the migration of breast cancer cells by regulating the release of autocrine EVs." (PMID 38987765, 2024). "Suppression of DENND10 expression resulted in reduced secretion of EVs and impaired cell motility in breast cancer cells." (PMID 38987765, 2024). "In the current study, we showed that DENND10 is important for the migration and invasion of breast cancer cells by regulating both the quantity and composition of EVs." (PMID 38987765, 2024). "To decipher the role of DENND10 in breast cancer cells, we knocked out the Dennd10 gene in 4T1 cells, a highly metastatic triple-negative breast cancer cell line, using lentivirus-based CRISPR/Cas9 gene editing." (PMID 38987765, 2024). "DENND10 knockout (DENND10-KO) in breast cancer cells led to defective EV biogenesis due to impaired endolysosomal trafficking." (PMID 38987765, 2024). "This suggests that DENND10's influence on disease progression may manifest differently depending on the subtype of breast cancer, with particular importance in highly aggressive cancers." (PMID 38987765, 2024). "In addition, analysis of the CCLE (Cancer Cell Line Encyclopedia) database revealed that DENND10 expression was higher in human breast cancer cell lines derived from metastatic sites compared to those from primary sites, strongly suggesting that DENND10 might be involved in breast cancer metastasis." (PMID 38987765, 2024).
gastric cancer (1 paper, 2024). A primary or metastatic malignant neoplasm involving the stomach. "A similar correlation was also observed in gastric cancer patients, where high DENND10 expression was significantly associated with poor overall survival (p = 0.006) and a short duration of time to first-progression (p = 0.0018)." (PMID 38987765, 2024).
metastatic cancer (1 paper, 2024). A carcinoma which has spread from the original site of growth to another anatomic site. "Our study underscores the importance of autocrine EV in tumor microenvironment and also reveals DENND10 as a potential target for metastatic cancer." (PMID 38987765, 2024).
triple-negative breast carcinoma (1 paper, 2024). An invasive breast carcinoma which is negative for expression of estrogen receptor (ER), progesterone receptor (PR), and human epidermal growth factor receptor 2 (HER2). "Additionally, we knocked down DENND10 expression in another metastatic triple-negative breast cancer cell line, MDA-MB-231." (PMID 38987765, 2024).
tumor (2 papers, 2019 to 2024). "In conclusion, this study unveiled novel physiological functions for the ancient protein DENND10, which plays a critical role in the coordination between the release of autocrine EVs and tumor cell migration." (PMID 38987765, 2024). "As EVs are critical components of tumor microenvironment, we wondered whether DENND10 is involved in the progression of any type of cancer." (PMID 38987765, 2024). "Taken together, our study showed that DENND10 regulates both the quantity and composition of autocrine tumor EVs, which contribute to the deposition of cargoes, particularly extracellular matrix proteins, within the tumor microenvironment, thereby facilitating efficient cell migration." (PMID 38987765, 2024). "In summary, our study unveiled DENND10 as an intrinsic regulator of cell migration that modifies the tumor microenvironment through autocrine EV release, which could be exploited for developing targeted therapies for tumor metastasis." (PMID 38987765, 2024). "DENND10 belongs to the family of DENN (differentially expressed in normal cells and neoplasia) domain-containing proteins, the largest family of guanine nucleotide exchange factors (GEFs) for Rab small GTPases." (PMID 38987765, 2024).
cancer (1 paper, 2024). A tumor composed of atypical neoplastic, often pleomorphic cells that invade other tissues. "First, we analyzed the association between DENND10 expression and the survival of cancer patients with KM Plotter, a web-based portal that integrates clinical data from multiple sources, including GEO, EGA, and TCGA." (PMID 38987765, 2024). "We also determined the effect of DENND10 deletion on cancer metastasis in vivo." (PMID 38987765, 2024). "The current study aims to decipher the role of endosomal protein DENND10 in cancer development." (PMID 38987765, 2024). "We next sought to understand the mechanism by which DENND10 regulates cancer cell migration." (PMID 38987765, 2024).
DENND10 also shares sentences with these, for which no sentence is quoted: Cerebellar hypoplasia (1 paper).